BUB1 (BUB1 mitotic checkpoint serine/threonine kinase)
Diseases named in the same sentence as BUB1 in open-access papers (continued):
Sharing a sentence is not in itself a finding about the gene and the disease.
tumor (continued). "The protein expressions of most of these genes were higher in UCEC tissues compared to non-tumor tissues, according to the Human Protein Atlas database, except that no protein expression was detected for KIF2C gene and there was no expression data for BUB1 gene in this database." (PMID 34868993, 2021).
infection (4 papers, 2009 to 2020). The state of being infected such as from the introduction of a foreign agent such as serum, vaccine, antigenic substance or organism. "Repair of virus-induced DNA damage is critical for cell survival from IAV infection, and several DNA damage response-associated genes (Bub1, Ddit4, Pml) were found to be infection-specific." (PMID 32790753, 2020). "Bub1 has a conserved function to facilitate endocytosis-dependent pathogenic infection." (PMID 29976667, 2018). "However, not limited to DCV, deficiency of bub1 also protected flies from infection by other endocytosis-dependent pathogens, such as VSV and Listeria." (PMID 29976667, 2018). "Furthermore, spatiotemporal colocalization between Bub1 and endocytic complex components along with pathogen infection also need deep analysis." (PMID 29976667, 2018). "Interestingly, DCV stimulation promoted the Bub1 protein to form large puncta in 43% of S2* cells, compared with only 8% before infection." (PMID 29976667, 2018). "Thus, down-regulation of Bub1 by the introduction of miR-450a-3p-mimic was successfully rescued by Ad-Bub1 infection." (PMID 23110129, 2012). "Thus, our data demonstrated a previously unknown function of Bub1 that could be hijacked by pathogens to facilitate their infection and spread." (PMID 29976667, 2018). "Therefore, bub1 is required for DCV infection and enhances the mortality and morbidity of flies after infection." (PMID 29976667, 2018).
adenocarcinoma (2 papers, 2016 to 2018). A common cancer characterized by the presence of malignant glandular cells. "Gene-expression analysis in adenocarcinomas based on microarray data showed that VRK1 was correlated with members of the mitotic cell-cycle gene network, including CENP-A, CENP-K, CENP-N, CENP-Q, Bub1, BubR1, SMC2, and CAP-G." (PMID 27231315, 2016).
neurodevelopmental disorder (2 papers, 2022 to 2024). A behavioral and cognitive disorder with onset during the developmental period that involves impaired or aberrant development of intellectual, motor, or social functions. "Here, we describe the first two patients with biallelic germline mutations in BUB1, which cause a previously unknown autosomal recessively inherited neurodevelopmental disorder." (PMID 35044816, 2022).
BUB1 also shares sentences with these, for which no sentence is quoted: acute myeloid leukemia (4 papers); adenoid cystic carcinoma (2); anaplastic thyroid carcinoma (2); invasive breast carcinoma (2); leukaemia (2); non-small cell lung carcinoma (2); pancreatic adenocarcinoma (2); adrenocortical carcinoma (1); alcohol dependence (1); aortic stenosis (1); ataxia telangiectasia (1); autism (1); autosomal recessive primary microcephaly (1); benign breast tumors (1); borderline serous ovarian neoplasms (1); brain glioma (1); breast (1); breast adenocarcinoma (1); chronic myeloid leukemia (1); endometrioid endometrial carcinomas (1); esophageal squamous cell carcinoma (1); familial colorectal cancer (1); Fanconi anemia (1); fibrosarcoma (1); gonadotroph adenomas (1); gynecological tumors (1); head and neck cancer (1); hepatitis B (1); Hepatitis C infection (1); hepatoblastoma (1).
A further 30 diseases each share a sentence with BUB1 in 1 paper.